STAT3 (signal transducer and activator of transcription 3)
Diseases named in the same sentence as STAT3 in open-access papers (continued):
Sharing a sentence is not in itself a finding about the gene and the disease.
glioblastoma (continued). "In glioblastoma, for instance, EZH2 interacts with and post-translationally methylates the tumor-promoting inflammatory transcription factor STAT3, thus increasing its transcriptional activity." (PMID 35884510, 2022). "UL33 also activated STAT3 in HTR-8SVneo cells, consistent with findings in HEK293T cells and in glioblastoma U251 cells." (PMID 35215985, 2022). "The resulting expression levels indicate that LINC00152 positively influences STAT3 expression also in A172 glioblastoma cells, by a direct interaction between LINC00152-RNA and STAT3-pre-mRNA (detected by ChIRP experiments)." (PMID 34531451, 2021). "Overexpression of TRIM8 leads to the higher expression of p-STAT3, c-MYC, SOX2, NESTIN, and CD133, and enhances self-renewal of glioblastoma stem cells." (PMID 33923045, 2021). "A prognostic model for glioblastoma patients stemmed out from a Cox multiple analysis, highlighting the role of MDSC, p-STAT3, and ARG1 activity together with clinical parameters in predicting patient’s outcome." (PMID 35069595, 2021). "In glioblastoma multiforme, EZH2 binds to STAT3 enhancing STAT3 activity by increased tyrosine phosphorylation of STAT344." (PMID 34376807, 2021). "miR-1246 has been identified as the most enriched miRNA in glioblastoma-derived exosomes and mediates glioblastoma-induced protumorigenic macrophage formation by targeting TERF2IP and subsequently activating the STAT3 pathway." (PMID 34532286, 2021). "Protein kinase B (PKB)/AKT-induced pS21 EZH2 was capable of accelerating EZH2-STAT3 intercommunication, stimulated EZH2-mediated STAT3 methylation, and augmented STAT3 activity in glioblastoma multiforme (GBM) stem-like cells (GSCs)." (PMID 34745848, 2021). "U87 glioblastoma cells migration was found induced with TGF-β (vehicle condition), whereas pharmacological inhibitors of STAT3, including AG490, tofacitinib, and EGCG, collectively prevented that increase." (PMID 34884812, 2021). "Our group found that miR-124 inhibited multiple targets in the signal transducer and activator of transcription 3 (STAT3) signaling pathway and reversed immune dysfunction of T cells induced by glioblastoma stem cells (GSCs)." (PMID 34532286, 2021). "Further study demonstrated that cryptotanshinone, an essential component of Radix Salviae, played a significant role in killing human glioblastoma cells and protecting the body by inhibiting the AKT, IKB, and STAT3 signaling pathways." (PMID 35154340, 2021). "This proof of concept indicates that targeting CD109/STAT3 axis sensitizes the highly resistant GSCs to chemotherapy, supporting an important role for CD109 in conferring chemoresistance of glioblastoma." (PMID 33986188, 2021). "Suppression on STAT3 phosphorylation and EGFR/Akt/cyclin D1 signaling was reported to jointly contribute to cell cycle arrest in glioblastoma cells." (PMID 32877289, 2020). "In human glioblastoma U251 cells, EGCG promotes apoptosis and blocks cell-growth because of inhibiting the JAK2/STAT3 signaling pathway." (PMID 32075265, 2020). "In glioblastoma stem-like cells (GSC), Akt-induced pS21-EZH2 can facilitate EZH2-STAT3 interaction, enhancing EZH2-mediated methylation and activity of STAT3, which accelerates GSC self-renewal and glioblastoma tumor progress." (PMID 32448308, 2020). "The STAT3/Slug axis is also connected to EMT phenotypes and cancer stemness that contribute to radioresistance in glioblastoma." (PMID 32872659, 2020). "To investigate the roles of STAT3 on CSC properties and metastatic capabilities in glioblastoma patients, we analyzed the database of TCGA Research Network." (PMID 32183406, 2020). "Treatment with ODZ10117 effectively suppressed the tyrosine phosphorylation and nuclear translocation of STAT3, resulting in the effective inhibition of migration, invasion, stem cell properties, and MES signatures in glioblastoma cells and GSCs." (PMID 32183406, 2020).
glioblastoma (continued). "TFDs designed envisaging cancer therapy include TFDs targeting NF-KB for inhibition of metastasis, signal transducer and activator of transcription 3, or STAT3, to induce apoptosis and cell cycle arrest in ovarian, glioblastoma, lung and neck cancers." (PMID 32151052, 2020). "Rac knockdown abolished STAT3 and ERK1/2 activation, and consequently impaired glioblastoma cell proliferation." (PMID 32915198, 2020). "Leptin has been shown to upregulate various intracellular signaling pathways linked to excessive proliferation, growth, migration, and invasion in various glioblastoma cell lines including NF-κB, p38-MAP Kinase, JAK/STAT3 and PI3K/Akt/mTOR/P70S6K." (PMID 33316976, 2020). "It inhibits proliferation, sphere forming and colony forming abilities of glioblastoma and liver cancer stem cells by ROS mediated activation of MAPK pathway, suppression of NF-κB signaling, downregulation of STAT3 activity and IAP family members." (PMID 33217990, 2020). "Collectively, the results demonstrated that stellettin B downregulates p-Stat3 and HIF-1α inhibits VEGF expression and secretion in glioblastoma cells." (PMID 30769863, 2019). "We demonstrate that RNA isolated from pseudopodia of hGCs contains migration-specific transcripts including Cdc42, Cofilin-1, Ezrin, Ilk, Limk, STAT3, MMP2, and Itgb1, recently described as part of intracellular pathways related to glioblastoma migration." (PMID 30353164, 2019). "Furthermore, Stat3 is an activator of the epithelial-mesenchymal transition (EMT) process in glioblastoma, both through TGFβ and HIF-1α, thus enhancing tumour high motility, invasiveness and chemo resistance, which could account for the positivity of cells at the invasion front." (PMID 31690341, 2019). "p21 has been shown to bind to and inhibit the oncogenic transcription factor, Stat3, a known target of TGF-β in glioblastoma and driver of GSC self-renewal and proliferation." (PMID 31602000, 2019). "Previous studies have identified STAT3 and CEBP-β as principal regulators of the mesenchymal gene expression signature in glioblastoma." (PMID 30621209, 2019). "A novel aptamer-siRNA chimera (Gint4.T-STAT3) was developed to deliver STAT3 siRNA efficiently and subsequently suppressed the expression of STAT3 in PDGFRβ+ glioblastoma multiforme (GBM) cells, through in vitro and in vivo studies, demonstrating that this is an effective strategy." (PMID 30847297, 2019). "For human glioblastomas, cervical and colon carcinoma cells downregulation of PTEN and activation of Akt and STAT3—mediated by increased levels of hsa-miRNA-221-3p—have been shown as key players in tumor cell survival and radio- and chemoresistance." (PMID 31467538, 2019). "Phosphorylated Stat3 is highly expressed in between 8.6% and 83.3% of patients with GBM and affects tumor angiogenesis and migration in hypoxically stressed glioblastoma." (PMID 30769863, 2019). "A study claimed that leptin receptor-positive glioblastoma cells were resistant to chemotherapy with temazolamide (TMZ) which failed to arrest cell proliferation and initiate apoptosis via STAT3 signaling." (PMID 30803210, 2019). "To investigate the antiangiogenetic mechanism of stellettin B, we detected the protein expression of HIF-1α, p-Stat3, and the downstream angiogenesis effector, VEGF, which was inhibited by stellettin B treatment in glioblastoma cell lines." (PMID 30769863, 2019). "This increased STAT3 activity can contribute to GSC self-renewal and glioblastoma multiforme malignancy." (PMID 30926778, 2019). "The transcription factor STAT3 is activated in ~70% of haematological and solid tumours, including HNSCC, glioblastoma and pancreatic cancer." (PMID 31817106, 2019). "It is known that STAT3 works as a regulator favoring tumor formation in different tumor types including leukemia, colon and renal carcinomas, breast cancers, and glioblastoma multiforme (GBM)." (PMID 30340426, 2018).
glioblastoma (continued). "In glioblastoma multiforme (GBM), STAT3 has been well documented as a facilitator of tumour cell proliferation, invasion, and angiogenesis and is an essential factor that maintains the stem cell phenotype of GSCs." (PMID 29182544, 2017). "Several glioblastoma studies have reported elevated levels of IL-6, IL-10 and TGF-β along with higher STAT3 activity." (PMID 28346397, 2017). "We showed that Rac proteins promote the STAT3 and ERK activation and enhance cell proliferation and colony formation of glioblastoma stem-like cells." (PMID 28160553, 2017). "While PIAS proteins can be overexpressed in some cancers, PIAS3 expression is repressed in anaplastic lymphoma, glioblastoma, mesothelioma, and NSCLC, which correlates to constitutive STAT3 activation." (PMID 27148255, 2016). "As overexpressed in glioblastoma stem cells (GSCs), ETK activates STAT3 to maintain self-renewal and tumorigenic potential of GSCs." (PMID 25849286, 2015). "A recent study reported an increased radiosensitivity in constitutively STAT3 expressing glioblastoma multiforme cell line-derived CD133+ cells and GBM-CD133+ xenografts following treatment with the STAT3-inhibitor AG490 and resveratrol (RV)." (PMID 25268165, 2014). "In glioblastoma, it has been shown that the stem cell factor EZH2 interacts with STAT3 and tri-methylates its K180 residue, thereby activates STAT3 and promotes tumorigenesis." (PMID 24995504, 2014). "Dual targeting of STAT3 and APE1 is not only efficacious in PDAC; we also observed significant synergy in glioblastoma cells (Fishel, Kelley, manuscript in preparation)." (PMID 23094050, 2012). "IL-20 treatment also induced the activation of Jak2/Stat3 and ERK1/2 pathway in GBM8901 glioblastoma cells." (PMID 22962576, 2012). "Several medulloblastoma and glioblastoma cell lines which overexpress phosphorylated STAT3 (Daoy, UW426, UW288-1, U87 and U87Δ) were used to evaluate the effects of LLL12 on STAT3 phosphorylation and the induction of apoptosis." (PMID 21526200, 2011). "Moreover, since STAT3 signaling is a downstream effector of interleukin-6 (IL-6), blocking IL-6R alpha or IL-6 expression in GSCs by shRNAs suppresses tumor sphere formation capacity and increases the survival of mice bearing intracranial glioblastoma xenografts." (PMID 24212792, 2011). "In ObR-positive glioblastoma cell lines LN18 and LN229, leptin stimulates cell proliferation and induces STAT3 and Akt pathways as well as inactivates the cell cycle suppressor Rb." (PMID 21771332, 2011). "In addition to aberrant PI3K/Akt signaling; heightened STAT3 activation plays a critical role in glioblastoma and STAT3 inhibitors have shown promise as therapeutics for GBM." (PMID 20576128, 2010). "Additionally, the STAT3 pathway is described as upstream of NEAT1, binding to and activating the NEAT1 promoter in glioblastoma." (PMID 40170567, 2025). "MerTK activates the STAT3/KRAS and SRC signaling cascades in glioblastoma multiforme (GBM)." (PMID 41195524, 2025). "In addition, TSPAN6 induced STAT3 activation of vascular endothelial cells and promoted angiogenesis in TME of glioblastoma." (PMID 38725860, 2024). "There is no study in the literature investigating Stat3 expression after NP and DX treatment used in glioblastoma treatment." (PMID 39459502, 2024). "In the cell death pathway, EGF treatment induces apoptosis via AKT1 inhibition in EGFR overexpressed dominant-negative Ras mutant cell lines, or via phosphorylation of STAT3 in glioblastoma; however, the mechanisms for these pathways are not clear." (PMID 38789573, 2024). "Furthermore, PLD can repress glioblastoma cell migration and invasiveness by inhibiting the EGFR/AKT/ERK1/2/STAT3/SOX2/Snail signaling pathway." (PMID 39408901, 2024).
glioblastoma (continued). "In addition, STAT3 was shown to be a positive regulator of HIF1α, VEGF, MMP-2 and TWIST in hypoxic glioblastoma and its suppression induced proliferation arrest and apoptosis in glioblastoma cells." (PMID 38654280, 2024). "In malignant glioblastoma cell lines, the levels of phosphorylated JAK1, JAK2, and STAT3 were uniformly upregulated with FAK and positively correlated, followed by the levels of phosphorylated p38, JNK and ERK1/2 downregulated, and the trend was reversed after treatment." (PMID 38240856, 2024). "Moreover, bioinformatics analyses in TCGA glioblastoma dataset confirmed that LDHA, YAP1, STAT3, CCL2, and CCL7 positively correlated with each other and with macrophage signature in patient tumors." (PMID 38443336, 2024). "In this study, we hypothesized that TSPAN6 might promote the biogenesis of exosomes via STAT3 pathway in glioblastoma cells, and subsequently regulate angiogenesis in TME by STAT3." (PMID 38725860, 2024). "In addition, TSPAN6 overexpression in glioblastoma cells enhanced angiogenesis via regulating TME and STAT3 signaling pathway." (PMID 38725860, 2024). "Furthermore, TSPAN6 promoted the malignant progression of glioblastoma by interacting with CDK5RAP3 and regulating STAT3." (PMID 38725860, 2024). "Thus, TSPAN6 promotes cancer progress by STAT3 signaling pathway in glioblastoma cells, and TSPAN6 also regulates angiogenesis via exosome through STAT3 pathway in TME." (PMID 38725860, 2024). "In glioblastoma models, co-culturing glioblastoma cells with microglia resulted in significantly higher LCN2 levels and increased nuclear NFκB and STAT3 phosphorylation compared to monoculture, suggesting that microglia stimulate glioblastoma through LCN2 modulation." (PMID 39188682, 2024). "Leptin/STAT3/Notch axis enhances CD133 levels, clonogenic and self-renewal capacity, whereas STAT3 inhibitor, γ-gamma secretase inhibitor, and leptin antagonist (LDFI), abrogated leptin effect on stem cells functions in glioblastoma." (PMID 37922108, 2024). "In addition to STAT3, resveratrol also modulates the JAK/STAT signaling axis, which is critical for glioblastoma pathogenesis." (PMID 39769099, 2024). "In glioblastoma, tri‐partite motif‐containing protein 8 (TRIM8) and nuclear-Smad6 arbitrate the ubiquitination that persuades degradation of PIAS3, which in turn promotes STAT3 activation." (PMID 38590645, 2024). "Subsequently, their results indicated that miR-519a enhanced chemosensitivity in glioblastoma cells, primarily through TMZ-induced autophagy and apoptosis, by targeting the signal transducer and activator of transcription 3 (STAT3)/B-cell lymphoma 2 (Bcl-2) signaling pathway." (PMID 37860265, 2023). "Furthermore, in addition to affecting the JAK2/STAT3 pathway, JSI-124 was also found to activate the NF-κB pathway to induce apoptosis in human glioblastoma cells." (PMID 38001999, 2023). "Furthermore, it has been reported that the activation of the signal transducer and activator of transcription 3 (STAT3) through the interaction of CD109 and glycoprotein 130 (GP130) promotes plasticity and chemoresistance in glioblastoma stem cells." (PMID 37373457, 2023). "Moreover, a recent study on glioblastoma found that the phosphatidylinositol 3-kinase enhancer A (PIKE-A) mediates the binding of the signal transducer and activator of transcription 3 (STAT3) with the G6PD promoter, leading to enhanced G6PD expression." (PMID 38139067, 2023). "In glioblastoma multiforme (GBM), which is often treated with concurrent chemoradiotherapy with temozolomide, EZH2 binds to and methylates STAT3, leading to enhanced STAT3 activity by phosphorylation of STAT3 and promoting the tumorigenicity of GBM stem-like cells." (PMID 37121970, 2023). "Furthermore, BACE1 reduced the phagocytosis of tumor cells in glioblastoma by activating the tumor-promoting macrophages via cleaving interleukin-6 receptor (IL-6R) and activating IL6/sIL-6R/STAT3 signaling." (PMID 38201438, 2023).
glioblastoma (continued). "In this study, our results revealed that interfering with HA synthesis in glioblastoma or inhibiting the binding of HA to CD44 on macrophages inhibits M2 macrophages polarization and activates M1 macrophages polarization by regulating STAT3 and STAT1 phosphorylation." (PMID 35410993, 2022). "Because we showed a decrease in the migration capacity of glioblastoma cells under treatment with miR‐218 in our studies, we could conclude then that these changes might be the result of the impact of miR‐218 on CDC42, STAT3, EGF and CTTN." (PMID 35702951, 2022). "In glioblastoma cells, paeoniflorin treatment can suppress tumor cell migration and invasion and actin cytoskeleton rearrangement by inhibiting c-Met-mediated RhoA/ROCK signaling and EMT, deactivating STAT3 signaling, or increasing miR-16 expression." (PMID 36046834, 2022). "Taken together, the present study reveals a novel mechanism by which PIKE-A promotes tumor growth and demonstrates that PIKE-A regulates SDHA expression by promoting the STAT3/FTO axis, thereby promoting mitochondrial function and cell proliferation in glioblastoma." (PMID 36232604, 2022). "Therefore, the MSI1/miR-671-5p/STAT3 axis enhances radioresistance, and the MSI1/miR-671-5p/TRAF2 axis activates glioblastoma stem cell-like properties and EMT-like abilities." (PMID 35052701, 2021). "Therefore, we performed an analysis of the mRNA expression of CD109 and the key mediators of the STAT3 signaling pathway (IL6ST/GP130, STAT3, and IL6) in the Human Glioblastoma Cell Culture (HGCC) data set." (PMID 33986188, 2021). "Intriguingly, p-STAT5, p-ERK, and p-STAT3 signaling profiles reminiscent of the negative prognostic cells from glioblastoma have been seen in leukemia and ovarian cancer." (PMID 32573435, 2020). "The mRNA level of STAT3 was higher in glioblastoma compared to non-tumor, astrocytoma, and oligodendroglioma, and was positively correlated with the grade of brain tumor." (PMID 32183406, 2020). "Tyrosine phosphorylated STAT3 was effectively inhibited following incubation with >20 μM ODZ10117 for over 12 h and with 40 μM ODZ10117 over for 1 h in glioblastoma and primary glioblastoma cell lines." (PMID 32183406, 2020). "In glioblastoma, glioma-derived exosomal miR-148a promoted the proliferation and spread of glioblastoma cells via targeting CADM1 (cell adhesion molecule 1), thus activating STAT3 pathway." (PMID 31752198, 2019). "Moreover, the MET/PKCδ/SRC/STAT3 signaling axis can activate subsequent NOTCH2 signaling, and ultimately leads to increased invasiveness of glioblastoma cells." (PMID 31221203, 2019). "It has been reported that the histone methyltransferases EZH2, which methylates H3K27, modifies the nonhistone protein by directly binding to STAT3 in glioblastoma." (PMID 31636512, 2019). "Furthermore, our results are consistent with previous studies that already described a reduction of survivin in glioblastoma, leukemia, NSCLC, breast and ovary cancers when JAK/STAT3 pathway was inhibited." (PMID 31412593, 2019). "Moreover, stellettin B downregulates VEGF mediators, Stat3 and HIF-1, which leads to the inhibition of the expression and secretion of the major angiogenesis inducer, VEGF, in glioblastoma cell lines." (PMID 30769863, 2019). "Evidence showed that EZH2 could bind to Stat3, and the EZH2-Stat3 interaction led to enhance Stat3 activity in glioblastoma cells." (PMID 28360411, 2017). "Based on these observations and the STAT3 inhibition phenotype, we investigated the possibility that the H3K27 demethylase Jmjd3 may mediate effects of STAT3 in glioblastoma stem cells." (PMID 28384648, 2017). "Via the stabilization of the transcription factor STAT3 (signal transducer and activator of transcription 3) overexpressed BAG3 may confer stem-cell like characteristic on glioblastoma cells." (PMID 28680391, 2017).